TRBV28 (T cell receptor beta variable 28)
Description:
V region of the variable domain of T cell receptor (TR) beta chain that participates in the antigen recognition. Alpha-beta T cell receptors are antigen specific receptors which are essential to the immune response and are present on the cell surface of T lymphocytes. Recognize peptide-major histocompatibility (MH) (pMH) complexes that are displayed by antigen presenting cells (APC), a prerequisite for efficient T cell adaptive immunity against pathogens. Binding of alpha-beta TR to pMH complex initiates TR-CD3 clustering on the cell surface and intracellular activation of LCK that phosphorylates the ITAM motifs of CD3G, CD3D, CD3E and CD247 enabling the recruitment of ZAP70. In turn ZAP70 phosphorylates LAT, which recruits numerous signaling molecules to form the LAT signalosome. The LAT signalosome propagates signal branching to three major signaling pathways, the calcium, the mitogen-activated protein kinase (MAPK) kinase and the nuclear factor NF-kappa-B (NF-kB) pathways, leading to the mobilization of transcription factors that are critical for gene expression and essential for T cell growth and differentiation. The T cell repertoire is generated in the thymus, by V-(D)-J rearrangement. This repertoire is then shaped by intrathymic selection events to generate a peripheral T cell pool of self-MH restricted, non-autoaggressive T cells. Post-thymic interaction of alpha-beta TR with the pMH complexes shapes TR structural and functional avidity.
Synonyms: TCRBV3S1; TCRBV28S1
Tractability: Antibody: UniProt places it where antibodies can reach, with medium confidence; UniProt predicts a signal peptide or a membrane-spanning region; its Gene Ontology location is reachable by antibodies, with medium confidence.
Gene: T-cell receptor variable (V) gene on chromosome 7 (142,720,660 to 142,721,160, forward strand). Ensembl gene ENSG00000211753.
Subcellular location: Cell membrane
Gene Ontology:
Molecular function: peptide antigen binding
Biological process: cell surface receptor signaling pathway
Cellular component: plasma membrane
Homologues: Orthologues: chimpanzee TRBV28 (82% identical), macaque TRBV28 (79% identical), mouse Trbv29 (68% identical), rat AC142181.1 (67% identical). Paralogues in human: TRBV27 (58% identical), TRBV10-3 (54% identical), TRBV19 (54% identical), TRBV10-2 (54% identical), TRBV25-1 (54% identical), TRBV6-1 (54% identical), TRBV10-1 (53% identical), TRBV6-2 (53% identical), TRBV24-1 (52% identical), TRBV6-7 (52% identical), TRBV6-4 (50% identical), TRBV6-5 (50% identical), and 39 more.
Diseases named in the same sentence as TRBV28 in open-access papers:
TRBV28 is named in the same sentence as 4 diseases in open-access papers, as found by Europe PMC text mining. Sharing a sentence is not in itself a finding about the gene and the disease. The quoted sentences say what the papers report.
melanoma (1 paper, 2009). A malignant, usually aggressive tumor composed of atypical, neoplastic melanocytes. "Conversely, other authors reported that the recognition of melanoma Ags involved the use of T lymphocytes bearing specific TRBV chains, such TRBV5, TRBV9, TRBV19, TRBV27, and TRBV28." (PMID 19317896, 2009).
infection (1 paper, 2025). The state of being infected such as from the introduction of a foreign agent such as serum, vaccine, antigenic substance or organism. "In line with this, the usage of the V and J genes was very similar during the course of infection, in which mainly genes from the TRBV28, TRBV27, and TRBV6 families, as well as the TRBJ1-01 gene, were detected." (PMID 40573882, 2025).
tumour (1 paper, 2018). "Here we show that the structures of two distinct TCRs (TRAV4+TRAJ21+-TRBV28+TRBJ2-3+ and TRAV4+TRAJ8+-TRBV9+TRBJ2-1+), originating from a polyclonal T-cell repertoire, bind to HLA-B*07:02, presenting a 13-amino-acid-long tumour-associated peptide, NY-ESO-160–72." (PMID 29531227, 2018).
TRBV28 also shares sentences with these, for which no sentence is quoted: breast carcinoma (1 paper).